AQP7 (aquaporin 7)
Diseases named in the same sentence as AQP7 in open-access papers (continued):
Sharing a sentence is not in itself a finding about the gene and the disease.
Hypertension (4 papers, 2018 to 2024). The presence of chronic increased pressure in the systemic arterial system. "To summarize, this study suggests that the genetic variants of AQP7 SNPs are associated with the risk of stroke among patients with hypertension in China." (PMID 32309443, 2020). "We aimed to investigate the associations between genetic variants in AQP7 and AQP9 and the risk of stroke among patients with hypertension, as well as to explore gene-gene and gene-environment interactions." (PMID 32309443, 2020). "Therefore, this study is aimed at investigating the associations between AQP7 and AQP9 genetic variants and the risk of stroke among patients with hypertension." (PMID 32309443, 2020). "However, limited epidemiological studies explore the associations between AQP7 and AQP9 and the risk of stroke among patients with hypertension in China." (PMID 32309443, 2020). "However, epidemiological studies on the associations between AQP7 and AQP9 and the risk of stroke among patients with hypertension are still largely lacking." (PMID 32309443, 2020). "In the cardiovascular system AQP1, AQP4, AQP7, and AQP9 are expressed in endothelial cells, vascular smooth muscle cells, and cardiac tissue which all play a vital role in the development and progression of pathologies such congestive heart failure, ischemia, hypertension, and angiogenesis." (PMID 30555637, 2018).
Infertility (3 papers, 2012 to 2026). "In men, a lack in AQP7 expression is associated with infertility and the AQP7-deficient sperm show significantly reduced motility." (PMID 40927981, 2026). "AQP3, -7, -8, and -11 are all present in sperm, with the expression levels/activity of AQP3 and AQP7 being shown to be reduced in asthenozoospermic individuals as a possible cause of infertility." (PMID 40927981, 2026). "While AQP-7 has a more active role in the beginning infertility period, later its action is slightly decreasing and stabilizing." (PMID 38812647, 2024). "Aquaporin 7 (AQP7) is known to be expressed in human sperm tails and lack of its expression has also been observed in some infertile patients." (PMID 22978562, 2012).
breast tumor (2 papers, 2015 to 2024). "This is in agreement with the previous findings that AQP7 expression was down-regulated in breast tumor and CIDEA and CIDEC are cell death-inducing DFFA-like effectors to activate apoptosis." (PMID 26618778, 2015).
Crohn disease (2 papers, 2016 to 2021). A gastrointestinal disorder characterized by chronic inflammation involving all layers of the intestinal wall, noncaseating granulomas affecting the intestinal wall and regional lymph nodes, and transmural fibrosis. "AQP4, AQP7 and AQP8 mRNAs were all detected in both normal colons and in the colons of patients with ulcerative colitis, Crohn’s disease and infectious colitis." (PMID 27589719, 2016).
gastritis (2 papers, 2016 to 2023). Inflammation of the stomach. "Collectively, these results indicate that the expression of several subtypes of AQPs (AQP1, AQP3, AQP4, AQP5, AQP7 and AQP11) is upregulated by gastritis, and more studies are essential to investigate their potentials as diagnostic biomarkers and drug targets for gastritis therapy." (PMID 27589719, 2016).
glioma (2 papers, 2020 to 2023). A benign or malignant brain and spinal cord tumor that arises from glial cells (astrocytes, oligodendrocytes, ependymal cells). "The qRT-PCR results showed that compared with HA1800, the mRNA expression levels of AQP7 in human glioma cell lines were generally decreased, while the mRNA expression levels of E2F7 were generally increased." (PMID 37091789, 2023).
ischemia (2 papers, 2018 to 2024). A hypoperfusion of the BLOOD through an organ or tissue caused by a PATHOLOGIC CONSTRICTION or obstruction of its BLOOD VESSELS, or an absence of BLOOD CIRCULATION. "AQP7 deficiency increases myocardial infarction size and apoptosis after ischemia." (PMID 37691043, 2024). "In study 3, intra-myocardial ATP content was compared before (sham) and after (control or STH2) ischemia in mature WT and AQP7-KO mice." (PMID 37691043, 2024). "Thomas’ Hospital No. 2 solution (STH2) is equally effective in both young and aged aquaporin-7-knockout (AQP7-KO) mice and the mechanisms by which the intra-myocardial adenosine triphosphate (ATP) content is altered during ischemia without aquaporin-7." (PMID 37691043, 2024).
male infertility (2 papers, 2012 to 2024). The inability of the male to effect fertilization of an ovum after a specified period of unprotected intercourse. "AQP7 positive sperm have significantly higher motility rate than that of AQP7 negative sperm, making this gene expression one of the deciding factors for male infertility." (PMID 22978562, 2012). "Moreover, the absence of AQP7 expression in sperm might potentially serve as a fundamental cause of male infertility." (PMID 39071790, 2024).
myocardial infarct (2 papers, 2024). "Additionally, studies on myocardial infarction in AQP7-KO mice revealed an increased area of myocardial infarction in their hearts, which may be related to glycerol transport." (PMID 39456161, 2024).
renal carcinoma (2 papers, 2022). A carcinoma arising from the epithelium of the renal parenchyma or the renal pelvis. "We had obtained that the mRNA expression level of AQP7 in ccRCC patients was significantly lower than that in normal tissues, and the mRNA expression level of AQP7 decreased with the increase of the grade of renal cancer." (PMID 35245343, 2022).
Sepsis (2 papers, 2023 to 2024). Sepsis is defined as life-threatening organ dysfunction caused by a dysregulated host response to infection. "In sepsis, increased intracellular glycerol levels or active AQP7 expression could enhance p38 signaling, which is associated with the upregulation of glycolysis and nitric oxide production." (PMID 39544938, 2024). "Recent studies suggest that AQPs, particularly aquaglyceroporins like AQP3, AQP7, AQP9, and AQP10, play pivotal roles in immune cell metabolism and offer new therapeutic avenues for sepsis treatment." (PMID 39544938, 2024).
acute promyelocytic leukemia (1 paper, 2024). An aggressive form of acute myeloid leukemia (AML), characterized by arrest of leukocyte differentiation at the promyelocyte stage, due to a specific chromosomal translocation t(15;17) in myeloid cells. "Cell proliferation was analyzed in the acute promyelocytic leukemia (APL) cell line NB4 which showed expression of all three aquaglyceroporins AQP3, AQP7, and AQP9." (PMID 38319972, 2024).
central obesity (1 paper, 2018). "Interestingly, we found that the associations of two AQP7 SNPs were evident in the subjects who were overweight or with central obesity." (PMID 30598999, 2018).
clear cell renal cell carcinoma (1 paper, 2022). "AQP7 was expressed at lower levels in clear cell renal cell carcinoma (fold change = −9.610, Gumz Renal, −2.102, Lenburg Renal), renal oncocytoma (fold change = −2.692), and renal pelvis urothelial carcinoma (fold change = −1.741) samples than in normal samples." (PMID 36254092, 2022).
Constipation (1 paper, 2025). Infrequent or difficult evacuation of feces. "In human, the expressions of AQP3 and AQP8 were upregulated in patients with constipation, whereas the expressions of AQP1, AQP7, and others were downregulated." (PMID 40807605, 2025).
endolymphatic hydrops (1 paper, 2024). An accumulation of endolymph in the inner ear (labyrinth) leading to buildup of pressure and distortion of intralabyrinthine structures, such as cochlea and semicircular canals. "Moxibustion at Tinggong (SI19) has been demonstrated to down-regulate plasma AVP, cochlear AQP2, and aquaporin 7(AQP7) expression in the animal model with endolymphatic hydrops, thereby achieving the effect of intervening in endolymphatic hydrops." (PMID 39722819, 2024).
enteritis (1 paper, 2016). Inflammation of the small intestine. "On the other hand, the downregulated expression of several AQPs (AQP1, AQP3, AQP4, AQP7, AQP8, AQP10 and AQP11) in the small and large intestines has been observed in the process of either enteritis or diarrhea." (PMID 27589719, 2016).
fibrosis (1 paper, 2020). the formation of excess fibrous connective tissue in an organ or tissue in a reparative or reactive process. "The analysis of the nine genes, namely A2m, Akr7a3, Aqp7, Ca3, Cdc2a, Cdkn3, Cyp2c11, Ntf3, and Sds, revealed the association between NGHCs and chronic inflammatory liver conditions, including liver cirrhosis and fibrosis." (PMID 32560183, 2020).
hemochromatosis (1 paper, 2026). A disorder of iron metabolism characterized by a triad of HEMOSIDEROSIS; LIVER CIRRHOSIS; and DIABETES MELLITUS. "As already discussed, glycerol reabsorption from urine is predominantly via AQP7, so that homozygous mutations of AQP7, or proximal tubule dysgenesis as occurs in neonatal hemochromatosis, can cause glyceroluria." (PMID 40927981, 2026).
leiomyosarcoma (1 paper, 2018). An uncommon, aggressive malignant smooth muscle neoplasm, usually occurring in post-menopausal women. "The leiomyosarcoma samples had different drug profiles but both demonstrated a mutation in AQP7." (PMID 29541442, 2018).
lipid metabolism disorders (1 paper, 2019). "A previous study had shown that AQP7 is up-regulated by fasting, low insulin and PPARα and altered expression may be related to lipid metabolism disorders." (PMID 31272371, 2019).
liver cancer (1 paper, 2019). An epithelial or non-epithelial malignant neoplasm that arises from the liver. "The study also found an upregulation of AQP9 and a downregulation of AQP3 (two molecules belonging to the same family of AQP7), indicating that the dysregulation of the aquaporine activity could play a fundamental role in the liver cancer development and progression." (PMID 31757200, 2019).
morbid obesity (1 paper, 2024). An excess of body weight, normally defined as an individual with a body mass index greater than 35 or a body weight greater than one hundred percent of ideal body weight. "The existence of the AQP7 34 kDa and 37 kDa isoforms has also been confirmed in the subcutaneous, abdominal, and visceral adipose tissues of adults with morbid obesity." (PMID 39456161, 2024).
nonalcoholic fatty liver (1 paper, 2019). "The purpose of this study was to investigate the effect of Qutanhuoxue decoction on AQP7 and AQP9 expression in nonalcoholic fatty liver model rats." (PMID 31275413, 2019).
osteosarcoma (1 paper, 2024). A usually aggressive malignant bone-forming mesenchymal neoplasm, predominantly affecting adolescents and young adults. "IFITM5, MMP13, PANX3, and MAGEA6 were some of the most overexpressed genes in osteosarcoma samples, while SLC4A1, HBA1, HBB, AQP7 genes were some of the top downregulated genes." (PMID 38966281, 2024).
Palmoplantar keratoderma (1 paper, 2023). Abnormal thickening of the skin of the palms of the hands and the soles of the feet. "These diseases include cataract (AQP0), autosomal recessive nephrogenic diabetes insipidus (AQP1 and AQP2) and palmoplantar keratoderma (AQP5) and diminished glycerol release (AQP7)." (PMID 36913438, 2023).
polycystic ovary syndrome (1 paper, 2018). A disorder that manifests as multiple cysts on the ovaries. "A significant increase in visceral WAT AQP7 expression was also found in a small cohort of insulin-resistant women with polycystic ovary syndrome (PCOS) characterized by endocrinological dysfunction, hyperandrogenism, absence of ovulation and polycystic ovaries." (PMID 29300344, 2018).
Polyuria (1 paper, 2021). An increased rate of urine production. "However, the deletion of AQP7 alone has been associated with glyceroluria and only mild polyuria." (PMID 34680152, 2021).
steatosis (1 paper, 2021). Increased lipid within the cytoplasm of cells. "Furthermore, NEAT1 could promote steatosis via enhancement of estrogen receptor-mediated AQP7 expression in HepG2 cells." (PMID 34078383, 2021).
Stroke (1 paper, 2020). Sudden impairment of blood flow to a part of the brain due to occlusion or rupture of an artery to the brain. "This study found that individuals carrying CTA haplotypes in AQP7 had a higher risk of stroke than those with the highest frequency of CCG haplotypes (OR 1.56, 95% CI 1.05-2.32)." (PMID 32309443, 2020). "This is the first study in China, which investigated the association between genetic variants in AQP7 and AQP9 and the risk of stroke among hypertensive patients." (PMID 32309443, 2020). "Dysregulations of AQP7 and AQP9 were found to be related to lipid metabolism abnormality, which had been proven to be one of the mechanisms of stroke." (PMID 32309443, 2020). "Dysregulation of AQP7 and AQP9 may result in lipid metabolism abnormality, which is one of the important mechanisms of stroke." (PMID 32309443, 2020).
tongue cancer (1 paper, 2026). A malignant neoplasm affecting the tongue. "CDC27 together with BCLAF1 and AQP7 show substantial changes in HPV-related tongue cancers, especially CDC27 deletions that correlate with tumour recurrence." (PMID 41487403, 2026).
tumor (18 papers, 2015 to 2026). "Subsequently in several real-world cohorts, increased AQP7 mRNA expression demonstrated a significant association with advanced tumor grade, stage, and lymphatic metastasis events, as well as poor prognosis in breast and liver cancers." (PMID 31493764, 2019). "The most commonly mutated gene was AQP7, mutated in >45% of all primary tumours." (PMID 35008243, 2021). "This gene encodes for Aquaporin 7, and there is some early evidence that it may play a role in tumour cell function." (PMID 29541442, 2018). "Both in vitro and in vivo experiments showed that AQP7 is required for proliferation, primary tumor progression, and metastasis." (PMID 39123442, 2024). "Lower expression of AQP7 in ccRCC tumor tissues was found in 4 datasets, and recombinational data analyses showed an obvious downregulation of AQP7 expression in ccRCC." (PMID 36254092, 2022). "MMTV-Wnt1 tumors also expressed low levels of Aqp7 but higher levels in more differentiated tumor tissue, where it localized to the epithelium most proximal to the stroma." (PMID 36212456, 2022). "AQP7 is regarded as a gateway for water and glycerol transportation, but little work has been performed on its involvement in tumor cell lipid metabolism." (PMID 35972604, 2022). "Five distinct EC clusters- stalk-like, tip-like, proliferative, arterial and AQP7+ ECs were present in the pooled ECs of both spontaneous and implanted tumour treated with PBS or cGAMP." (PMID 34285232, 2021). "Aqp7 knockdown significantly reduced primary tumor burden and metastasis." (PMID 39123442, 2024). "Aqp7 knockdown also significantly reduced primary tumor burden and metastasis." (PMID 36212456, 2022). "Moreover, the ECs retaining maturation gene profiles within tumours such as arterial, stalk-like and AQP7+ ECs are likely to be resistant to STING activation-induced apoptosis." (PMID 34285232, 2021). "In addition, 3 variants and 26 mutated genes, including CDC27, BCLAF1 and AQP7, were present in at least 30% of all primary tumours independent of prognosis." (PMID 35008243, 2021). "AQP7 and AQP9 expression levels are downregulated in HCC, and low expression levels of AQP7 are significantly positively correlated with tumor grade." (PMID 39048663, 2024). "Consistent with these Aqp7 results, in this study we discovered that therapeutic inhibition of AQP by Auphen treatment reduced the tumor growth and increased overall survival." (PMID 39123442, 2024). "It turned out that AQP7 was significantly positively correlated with immune, stromal, and ESTIMATE scores, but negatively correlated with tumor purity." (PMID 37091789, 2023). "C3-Tag tumor models had the highest expression of Aqp7, while MMTV-Neu and MMTV-PyMT tumors expressed low levels of Aqp7." (PMID 36212456, 2022). "We found that AQP1 (5.83e−07), AQP2 (0.0146), AQP4 (0.000382), AQP6 (0.0221), AQP7 (0.00052), AQP9 (8.2e−07) had significant correlations with the pathological stages of the tumor." (PMID 35245343, 2022). "In addition, the relations between the selected gene (AQP7 and E2F7) and tumor immune features also analyzed." (PMID 37091789, 2023). "Therefore, we infer that low expression of AQP7, which leads to an increased content of triglycerides, impaired glycerol and FFA transport, and reduced energy, inhibits the malignant behaviors of tumor cells." (PMID 35972604, 2022). "Among 6 significant hub genes, significantly decreased AGPAT9, AQP7, HMGCS2, KLF15, PPARGC1A mRNA expressions were found in ccRCC tissues compared with adjacent normal tissues, while MLXIPL mRNA expression was significantly elevated in tumor samples compared with normal samples." (PMID 31493764, 2019). "According to the GEPIA database, AQP1, AQP3, AQP4, and AQP9 were significantly expressed in LUAD tissues compared to normal lung tissues (p < 0.05), but some genes including AQP0, AQP5, AQP6, AQP7, AQP8, AQP10, and AQP11 were not differentially expressed between tumor and normal tissues." (PMID 34708074, 2021).